TGM2 (transglutaminase 2)
Diseases named in the same sentence as TGM2 in open-access papers (continued):
Sharing a sentence is not in itself a finding about the gene and the disease.
ovarian carcinoma (47 papers, 2011 to 2026). A malignant neoplasm originating from the surface ovarian epithelium. "In ovarian cancer, TGM2 interacts and activates the integrin-linked kinase (ILK) through phosphorylation at ILK Ser246, which subsequently activates β-catenin through the phosphorylation of glycogen synthase kinase-3α/β (GSK3α/β)." (PMID 39115570, 2024). "Expression of transglutaminase 2 (TGM2) has been linked to cisplatin resistance in ovarian cancer." (PMID 24212667, 2011). "Transglutaminase 2 (TG2) is a protein implicated in many biological and pathophysiological processes, including promoting tumor progression in ovarian cancer." (PMID 40777010, 2025). "Studies have shown that TGM2 is involved in the occurrence of cancer, and the expression of TGM2 in melanoma, pancreatic cancer, ovarian cancer, and other tumors is higher than that in normal tissues." (PMID 37115802, 2023). "Studies showed induction of cell death upon TGM2 expression and upon ablation of TGM2, as shown in breast, pancreatic, and ovarian cancer." (PMID 34103685, 2021). "TGM2 has been previously indicated in the pathogenesis of a number of cancers including ovarian cancer, however our finding of its highly increased concentration in EC plasma samples seems to be a new discovery." (PMID 31035965, 2019). "TGF-β-induced tissue transglutaminase (TGM2) promotes ovarian tumor metastasis in association with the induction of EMT and CSC/TIC phenotypes in ovarian cancer." (PMID 23528891, 2013). "TGM2 was found to be elevated in malignant tumors such as breast, colon, and ovarian cancers." (PMID 37270714, 2024). "In addition to regulating cell proliferation, TGM2 plays an important role in the migration and invasion of tumors; for example, the expression level of TGM2 is increased in breast, colon, and ovarian cancers, and the protein is up-regulated in metastatic lung cancer cells." (PMID 37115802, 2023). "Elevated expression of transglutaminase 2 (TGase 2, EC 2.3.2.13, protein-glutamine γ-glutamyltransferase, gene name TGM2) is known as one of the most upregulated genes during epithelial-mesenchymal transition (EMT) in ovarian cancer." (PMID 41629270, 2026).
diabetes (44 papers, 2008 to 2025). "For instance, IGFBP2, NPAS2, NDUFS7, and TGM2 showed differential expression in α cells from individuals with T2D and have previously been shown to affect diabetes and islet-related phenotypes or mitochondrial function." (PMID 36656641, 2023). "It should be noted that association of TGM2 mutations and dysfunction has not been confirmed in larger diabetes patient cohorts so far and TGM2 KO mice have no impairment in glucose-stimulated insulin secretion by pancreatic islets relative to wild-type littermates." (PMID 28248968, 2017). "Thus, although these mutations have not been found in 600 normoglycaemic controls, the heterozygous TGM2 mutations are not fully penetrant and do not appear to be the only cause of diabetes in these families." (PMID 23717413, 2013). "Transglutaminase 2 (TG2) activity contributes to endothelial dysfunction in the vasculature, a key independent predictor of vascular complications in diabetes, but the role of transglutaminases in human tissue remains underexplored." (PMID 39665157, 2025). "Critically, glomerular microvascular leakage and renal fibrosis were not detectable in kidneys of diabetic Tgm2−/− mice, demonstrating the important role of TGase2 in hyperglycemia-induced renal dysfunction in diabetes." (PMID 35054938, 2022).
autoimmune disease (42 papers, 2011 to 2026). A disorder resulting from loss of function or tissue destruction of an organ or multiple organs, arising from humoral or cellular immune responses of the individual to their own tissue constituents. "The expression of autoimmune phenomena, first of all the presence in the serum of anti-tissue transglutaminase 2 (anti-TG2) antibodies, and the strict association with autoimmune disorders suggested ESPGHAN to define CD as a systemic autoimmune disease." (PMID 32548124, 2020). "The presence of anti-tissue transglutaminase 2 (anti-TG2) antibodies in the serum, as well as the presence of autoimmune phenomena, account for the inclusion of CD among autoimmune diseases." (PMID 32548124, 2020).
Autoimmunity (40 papers, 2010 to 2025). The occurrence of an immune reaction against the organism's own cells or tissues. "Within humoral autoimmunity to neuronal antigens, anti-transglutaminase 2- or transglutaminase 6-related immunoglobulin depositions have been identified not only in the gut but also in the cerebellum, pons, medulla and around brain blood vessels." (PMID 25062250, 2014). "Based on the literature, autoantibodies were also tested against six potential organ–specific antigens implicated in T1D and/or other autoimmune conditions including ATP4B, TGM2, TPO, KCNRG, AQP-4, and GFAP." (PMID 23028856, 2012). "As mentioned in the introduction, TGM2 knockout mice show an autoimmune phenotype; at 15 months, 50% of mice were found to be terminally ill with immune complex glomerulonephritis, a consequence of autoimmunity due to the failure to clear apoptotic cells." (PMID 40610434, 2025). "We based our hypothesis on the fact that CD is an autoimmune disorder with systemic presentation (digestive and extradigestive) and on the recognition of transglutaminase 2 as the autoantigen in CD." (PMID 27446827, 2016).
glioma (40 papers, 2014 to 2024). A benign or malignant brain and spinal cord tumor that arises from glial cells (astrocytes, oligodendrocytes, ependymal cells). "TGM2 has been reported to be highly expressed in glioma tissues and therefore a possible diagnostic marker for glioma." (PMID 32765489, 2020). "Research has revealed that GK921, a TGM2-specific inhibitor, blocked mesenchymal transdifferentiation and showed significant therapeutic efficacy in a mouse model of glioma stem cells." (PMID 39654623, 2024). "TGM2 can regulate the proliferation of glioma cells by regulating the expression of ID1 through the PI3K/AKt pathway." (PMID 37115802, 2023). "More interestingly, the Gliovis database showed that FLOT1 was positively correlated with SDC1 expression and BHMT was positively correlated with TGM2 expression in glioma tissues." (PMID 37441590, 2023). "IR of the brain microenvironment, beside inducing senescence, also supports glioma stemness and survival via TGM2 (transglutaminase 2) secretion by astrocytes, and inhibition of PAF (PCNA-associated factor) turns those cells more sensitive to IR." (PMID 35626024, 2022). "Recently, we have shown that astrocytes respond to irradiation by becoming reactive; they secrete transglutaminase 2 into the extracellular matrix and thus increase the stemness and radiation resistance of glioma cells." (PMID 33802060, 2021). "Summarizing, despite of all difficulties we have identified two gene candidates for an universal GAM marker in experimental gliomas—Tgm2 and Gpnmb, which should be further investigated." (PMID 29963047, 2018). "The role of Tgm2 was also shown in tumorigenesis, as it is highly expressed by CD44high (stem cells marker) glioma tissue and Tgm2 inhibition lead to decrease of CD44high cells." (PMID 29963047, 2018). "The patient survival data mining demonstrated significant detrimental effect of TGM2 upregulation in glioma with a Log-rank p-value of 0.0068." (PMID 25247996, 2014). "In addition, TGM2 gene knockout inhibits the proliferation of glioma cells and reduces the expression of inhibitor of differentiation 1 (ID1), the downstream medium through which TGM2 regulates the proliferation of glioma cells." (PMID 37115802, 2023). "These bioinformatics analyses imply that the high level of SDC1 and TGM2 is a key factor of tumor radioresistance and may affect the outcome of radiotherapy of glioma patients." (PMID 37441590, 2023). "TGM2 overexpression triggers stem cell differentiation via PI3K/Akt signaling in glioma." (PMID 36831225, 2023). "For example, TGM2 could regulate angiogenesis and apoptosis via Wnt/β-catenin pathway in colorectal cancer and TGM2 inhibition reversed mesenchymal transdifferentiation by regulating C/EBPβ signaling in glioma stem cells." (PMID 33738254, 2021). "Importantly, TGM2 also supports the trans-differentiation of glioma stem cells by triggering degradation of CEBP Homologous Protein (CHOP/GADD153), leading to a reciprocal increase in CEBPβ levels." (PMID 33854178, 2021). "Collectively, these data suggest that HOTAIRM1 may promote glioma growth and therapy resistance by sponging hsa-miR-17-5p, and thereby increasing TGM2 transcript and protein levels." (PMID 34584066, 2021). "Additionally, the TGM2 gene locus is epigenetically silenced via methylation in some breast tumors and gliomas." (PMID 26956429, 2016). "The inhibition of TGM2 may impair cell proliferation and induced apoptosis in gliomas." (PMID 25247996, 2014). "In this study, we aimed to understand the relationship among SDC1, TGM2, FLOT1 and BHMT in modulating glioma autophagy and investigated their roles in regulating the radiosensitivity of glioblastoma by affecting the fusion of autophagosomes and lysosomes." (PMID 37441590, 2023). "Transglutaminase 2 levels are increased after IR in vivo and in recurrent HGG, and transglutaminase 2 inhibitors can counteract glioma proliferation." (PMID 34445646, 2021).
glioma (continued). "To investigate functional roles of reduced TGM2 expression in glioblastoma cells, we performed siRNA-mediated knock-down of TGM2 in LN-229 and SF126 glioma cells." (PMID 34584066, 2021). "More metastasis biomarkers such as TGM2, GBP1 and IGFBP7 were checked too, and all of their expressions have a positive correlation with the expression in CAV1 in all different types of gliomas." (PMID 37642765, 2023). "Moreover, it was shown that TGM2 is upregulated in the perinecrotic region of GBM and triggered mesenchymal transdifferentiation of glioma stem cells." (PMID 36354672, 2022). "However, recent evidence has also supported the potential role of radiation in transforming glioma’s TME into a tumor-permissive environment with astrocyte-derived transglutaminase 2 (TGM2) secreted by irradiated astrocytes contributing to tumor stemness and radioresistance." (PMID 37916170, 2023).
pancreatic cancer (39 papers, 2011 to 2025). "The expression of the transglutaminase 2 (TGM2) gene is generally associated with poor prognosis in pancreatic cancer and is involved in its initiation, inflammation, and progression, making it a target marker in studies analyzing drugs with chemosensitizing activity." (PMID 37765037, 2023). "Recent studies have shown that TGM2 protein also plays an important role in pancreatic cancer, and TGM2 promotes the growth and drug resistance of pancreatic cancer cells by influencing the ECM and stroma in the tumor microenvironment." (PMID 37115802, 2023). "To further investigate the role of TGM2 in pancreatic cancer, we performed IHC staining to examine TGM2 expression in tumor tissues." (PMID 33845796, 2021). "In pancreatic cancer cells, it induced apoptosis by activating tissue transglutaminase (TGM2) mediated Akt/mTOR signaling pathway that increased the ROS production in the cells." (PMID 34833937, 2021). "ROS production was significantly decreased upon overexpression of TGM2 in both the pancreatic cancer cell lines." (PMID 33845796, 2021). "TGM2 levels were significantly increased in PDAC tissues compared with normal tissues, and high TGM2 expression was positively correlated with poor prognosis in pancreatic cancer patients." (PMID 33845796, 2021). "TGM2 knockdown has been reported to inhibit the proliferation and invasion of pancreatic cancer cells." (PMID 34485257, 2021). "Over-activation of TGM2 in ATCs correlates with its observed over-expression in pancreatic cancer, another aggressive human malignancy with mortality rates close to 100%." (PMID 26680454, 2015). "TGM2 over-expression leads to tissue invasion, metastasis and chemotherapeutic resistance in cancers of the pancreas and is shown to protect these cancer cells from autophagy leading to growth advantage and resistance to chemotherapy." (PMID 26680454, 2015). "The Ozpolat and Akar's group reported that 2–4 μM Rottlerin induced autophagy through inhibition of PKCδ/transglutaminase 2 (TG2) in a panel of pancreatic cancer cells that are known to be resistant to most chemotherapeutic agents." (PMID 22272173, 2012). "In patients with pancreatic cancer, high TGM2 expression was positively associated with a poor prognosis.Kaempferol induces ROS-dependent apoptosis by downregulating TGM2 and the Akt/mTOR signaling pathway in PANC-1 and Mia PaCa-2 pancreatic cancer cells." (PMID 38324023, 2024). "The transglutaminase-2 gene (TGM2) has also been identified as an important extracellular cross-linking enzyme involved in ECM turnover, and its levels were associated with poor survival in pancreatic cancer patients." (PMID 37835519, 2023). "Kaempferol induces ROS-dependent apoptosis in pancreatic cancer cells via TGM2-mediated Akt/mTOR signaling, and TGM2 may represent a promising prognostic biomarker for pancreatic cancer." (PMID 33845796, 2021). "Based on biological analysis, we hypothesized that tissue transglutaminase (TGM2) gene was an essential target for kaempferol to induce ROS-related apoptosis in pancreatic cancer." (PMID 33845796, 2021). "In summary, the results of our present study indicate that kaempferol induces ROS-dependent apoptosis in pancreatic cancer cells via TGM2-mediated Akt/mTOR signaling, and TGM2 may represent a promising prognostic biomarker for pancreatic cancer." (PMID 33845796, 2021). "Meanwhile, our study firstly put forward that the high expression of TGM2 tracked with an immunosuppression-promoting phenotype and TGM2 is involved in the modulation of PD-L1 expression by regulating downstream transcription factor STAT3/NF-κB in pancreatic cancer cells." (PMID 33637086, 2021). "Given the crucial role of TGM2 in responding to oxidative stress, which involves various cellular processes, including apoptosis, we next investigated the potential functions of TGM2 in pancreatic cancer." (PMID 33845796, 2021).
pancreatic cancer (continued). "We hypothesized that TGM2 serves as a target of kaempferol to facilitate apoptosis, which may be correlated with ROS-dependent Akt/mTOR signaling in pancreatic cancer." (PMID 33845796, 2021). "Moreover, biocomputational tools allowed to demonstrate that among the most differentially expressed genes in pancreatic cancer were Mesothelin, Muc4, Muc5A/C, Kallikrein 10, Transglutaminase 2, Fascin, TMPRSS3 and Stratifin." (PMID 25275504, 2014). "Furthermore, LAMC2 and TGM2 have been found to promote the migration of pancreatic cancer cells." (PMID 34485257, 2021). "Furthermore, increased TGM2 mRNA expression was correlated with shorter OS and DFS, suggesting that TGM2 may serve as a prognostic biomarker for pancreatic cancer." (PMID 33845796, 2021). "To further confirm the efficacy of SEMet genes in pancreatic cancer metastasis, we examined the protein expression of EMT markers after TGM2 or DKK1 knockdown in two metastasis lesion-originated cell lines, CFPAC-1 and Patu 8988t." (PMID 37351165, 2023). "Drivers of collagen crosslinking in pancreatic cancer include the enzymes lysyl oxidase (LOX) and transglutaminase-2 (TGM-2)." (PMID 34205335, 2021). "Other groups have identified agents such as transglutaminase 2 and collagen to upregulate N-cadherin via JNK1 activation to promote EMT in pancreatic cancer cells." (PMID 28978088, 2017).
enteropathy (38 papers, 2008 to 2025). "It roughly affects 1% of the population, and presents with an enteropathy characterized by villous atrophy and intraepithelial lymphocytosis, as well as the presence of specific serum autoantibodies such as IgA anti-transglutaminase-2 (TTG) and anti-endomysium (EMA)." (PMID 39408713, 2024). "It is characterized by a variable combination of gluten-related signs and symptoms, and disease-specific transglutaminase 2 (TG2) and endomysial antibodies (EmA) in addition to enteropathy." (PMID 38337123, 2024).
melanoma (33 papers, 2011 to 2024). A malignant, usually aggressive tumor composed of atypical, neoplastic melanocytes. "Decreased proliferation of B16-F10 melanoma cells is associated with increased TGM2 overexpression, which is beneficial to melanoma formation and EMT." (PMID 37115802, 2023). "The tumor development mechanism varies in different cells; for example, in B16-F10 melanoma cells, the B16-F10 melanoma cell migration, adhesion, and invasion is associated with increased quinizolin, which induces TGM2 expression." (PMID 37115802, 2023). "Our analysis revealed significantly increased expression levels of the TGM2 gene in tumor samples compared to controls for melanoma, diffuse large B-cell lymphoma, and pancreatic adenocarcinoma." (PMID 38474044, 2024). "Studies have shown that TGM2 overexpression through drug-induced treatment can reduce the proliferation, survival, and migration of melanoma cells." (PMID 37115802, 2023). "The aGPCR GPR56/ADGRG1 regulates central nervous system myelination and melanoma progression by interacting with its ligand, tissue transglutaminase 2 (TG2), but the molecular basis for this interaction is largely undefined." (PMID 33037308, 2020). "They subsequently identified transglutaminase 2 (TG2) as the ECM-ligand of GPR56 in melanoma tissues." (PMID 30135857, 2018). "In humans, Tgm2 expression in melanoma samples were up to 24-fold during progressive stages." (PMID 35202347, 2022). "Hence, Tgm2 is related to inflammation and modulates the roles in various tumours, including melanoma." (PMID 35202347, 2022). "Interestingly, the TGM2 protein and mRNA levels were both reported to be elevated in metastases from breast and melanoma cancers." (PMID 31877708, 2019). "Inhibition of TGM2 has been reported to suppress melanogenesis in human melanoma cells." (PMID 26940175, 2016). "Finally, transglutaminase 2 plays a role in melanoma radioresistance, whereas the plasma membrane protein 5′-nucleotidase ecto (CD73) may favor melanoma immune escape via the CD73/adenosine axis." (PMID 37445731, 2023). "Diacylglycerol kinase (DGKB), TGc domain-containing protein (Tgm2), structural maintenance of chromosomes 4 (SMC4) and mastermind-like transcriptional coactivator 2 (MAML2) were related to lipid metabolism, facilitating melanoma development in the severe-EMN group." (PMID 35202347, 2022).